PI4K2A (phosphatidylinositol 4-kinase type 2 alpha)
Description:
Membrane-bound phosphatidylinositol-4 kinase (PI4-kinase) that catalyzes the phosphorylation of phosphatidylinositol (PI) to phosphatidylinositol 4-phosphate (PI4P), a lipid that plays important roles in endocytosis, Golgi function, protein sorting and membrane trafficking and is required for prolonged survival of neurons. Besides, phosphorylation of phosphatidylinositol (PI) to phosphatidylinositol 4-phosphate (PI4P) is the first committed step in the generation of phosphatidylinositol 4,5-bisphosphate (PIP2), a precursor of the second messenger inositol 1,4,5-trisphosphate (InsP3).
Synonyms: PI4KII; DKFZP761G1923; PIK42A; NEDMSB
Tractability: Small molecule: a structure with a bound ligand is known; a high-quality ligand is known. Antibody: UniProt places it where antibodies can reach, with high confidence; its Gene Ontology location is reachable by antibodies, with high confidence; the Human Protein Atlas places it where antibodies can reach. PROTAC: UniProt records ubiquitination sites on it; ubiquitination databases record sites on it; its protein half-life has been measured; a small molecule that binds it is known.
Target class: Enzyme; Transferase
Gene: Protein-coding gene on chromosome 10 (97,640,671 to 97,676,757, forward strand). Ensembl gene ENSG00000155252.
Subcellular location: Golgi apparatus, trans-Golgi network membrane; Membrane raft; Cell projection, dendrite; Presynaptic cell membrane; Synapse, synaptosome; Mitochondrion; Endosome; Endosome membrane; Cytoplasmic vesicle; Membrane; Cell membrane; Perikaryon; Cell projection, neuron projection
Subcellular location (Human Protein Atlas): Plasma membrane
Pathways (Reactome):
Metabolism: Synthesis of PIPs at the Golgi membrane; Synthesis of PIPs at the early endosome membrane; Synthesis of PIPs at the plasma membrane
Gene Ontology:
Molecular function: 1-phosphatidylinositol 4-kinase activity; AP-3 adaptor complex binding; ATP binding; protein binding; magnesium ion binding
Biological process: phosphatidylinositol biosynthetic process; phosphatidylinositol phosphate biosynthetic process; endosome organization; Golgi organization
Cellular component: BLOC-1 complex; cytoplasmic vesicle; early endosome membrane; endosome; endosome membrane; Golgi membrane; lysosomal membrane; membrane; membrane raft; plasma membrane; cytosol; dendrite; growing cell tip; mitochondrion; neuron projection; neuronal cell body; perikaryon; presynaptic membrane; trans-Golgi network; clathrin-sculpted vesicle; glutamatergic synapse; Golgi apparatus; presynaptic active zone; synapse
Genetic constraint (gnomAD): Loss-of-function variants: 17 observed, 37.38 expected, observed/expected ratio (o/e) 0.45, 90% interval 0.31 to 0.68. The upper end of that interval is the gene's LOEUF score, 0.68, which puts it in group 2 of 6, group 1 being the genes least tolerant of losing a copy. Missense variants: 390 observed, 486.59 expected, observed/expected ratio (o/e) 0.8, 90% interval 0.74 to 0.87. Synonymous variants: 206 observed, 206.02 expected, observed/expected ratio (o/e) 1, 90% interval 0.89 to 1.12.
Homologues: Orthologues: chimpanzee PI4K2A (100% identical), macaque PI4K2A (99% identical), pig PI4K2A (98% identical), guinea pig PI4K2A (97% identical), dog PI4K2A (97% identical), rabbit PI4K2A (96% identical), mouse Pi4k2a (95% identical), rat Pi4k2a (95% identical), tropical clawed frog pi4k2a (82% identical), zebrafish pi4k2a (77% identical), Drosophila melanogaster Pi4KIIalpha (55% identical), Caenorhabditis elegans ZC8.6 (49% identical). Paralogues in human: PI4K2B (58% identical).
Diseases named in the same sentence as PI4K2A in open-access papers:
PI4K2A is named in the same sentence as 29 diseases in open-access papers, as found by Europe PMC text mining. Sharing a sentence is not in itself a finding about the gene and the disease. The quoted sentences say what the papers report.
hereditary spastic paraplegia (4 papers, 2012 to 2023). Hereditary spastic paraplegias (HSP) comprise a genetically and clinically heterogeneous group of neurodegenerative disorders characterized by progressive spasticity and hyperreflexia of the lower limbs. "Thus, Pi4k2a signalling appears to be crucial for axonal integrity and therefore Pi4k2a has been proposed as a candidate gene for hereditary spastic paraplegia." (PMID 22392734, 2012). "Interestingly, a mouse KO for type II PI4K, Pi4k2a, develops late-onset features resembling hereditary spastic paraplegia (HSP), with severe axonal degeneration in the spinal cord that is associated with tremors, high-frequency nodding, spastic gait, limb weakness and urinary incontinence." (PMID 31413155, 2019).
breast carcinoma (3 papers, 2020 to 2022). "We evaluated the association between PKR (encoded as EIF2AK2) or PI4K2A gene expression and overall survival in breast cancer patients." (PMID 31554935, 2020). "We found that high levels of EIF2AK2 and PI4K2A gene expression were associated with low overall survival rates in breast cancer patients." (PMID 31554935, 2020). "In an analysis of data in TCGA, we found that high levels of EIF2AK2 and PI4K2A gene expression were associated with low overall survival rates in breast cancer patients." (PMID 31554935, 2020). "PKR / PI4K2A lysosome network is associated with poor prognosis in breast cancer patients." (PMID 32547879, 2020). "Recently, an increasing number of studies have identified PI4K2A as a potential target for breast cancer therapy." (PMID 31554935, 2020). "We observed that PKR and PI4K2A play significant prognostic roles in breast cancer patients." (PMID 31554935, 2020).
epilepsy (2 papers, 2022 to 2024). A brain disorder characterized by episodes of abnormally increased neuronal discharge resulting in transient episodes of sensory or motor neurological dysfunction, or psychic dysfunction. "Recent work shows that biallelic PI4K2A variants resulting in PI4K2A deficiency underlie developmental encephalopathy with epilepsy and hyperkinetic movement disorders." (PMID 38364889, 2024). "There is a remarkable overlap in the phenotypes of patients with pathogenic variants in PI4KA and PI4K2A, namely brain malformations, epilepsy and movement disorders." (PMID 35880319, 2022). "In the present study, we describe two patients from unrelated consanguineous families with PI4K2A deficiency characterized by developmental encephalopathy with hyperkinetic movement disorders, and epilepsy." (PMID 35880319, 2022). "The first and most striking report showed homozygous nonsense variants in PI4K2A in two affected siblings presenting with NDD, epilepsy, myoclonus, and akathisia." (PMID 35880319, 2022).
lung carcinoma (2 papers, 2023 to 2025). "EMT enhanced the vulnerability of lung cancer cells to PI4K2A small-molecule antagonists." (PMID 36757799, 2023). "PI4K2A is a therapeutically actionable driver of lung cancer progression." (PMID 36757799, 2023). "Based on our finding that PI4K2A depletion inhibited lung cancer progression, we speculated that PI4K2A activates a protumorigenic secretory process and initially addressed this possibility by performing conditioned medium (CM) transfer studies." (PMID 36757799, 2023). "Given that PI4K2A’s prognostic impact in non–small cell lung cancer (NSCLC) is histologic subtype specific, we assessed the biological role of PI4K2A in cell lines isolated from diverse NSCLC subtypes, including LUSC (CALU-1), large cell carcinoma (H1299), and LUAD (A549, H441, HCC827)." (PMID 36757799, 2023). "To determine which proteins are responsible for recruiting PI4KB in lung cancer cells, we conducted a biotin proximity labeling assay using TurboID-fused PI4KB or PI4K2A as the baits, revealing ACBD3 and ARMH3 as major PI4KB binding partners." (PMID 40189704, 2025). "To examine this possibility, we carried out siRNA-mediated depletion studies on PI4K2A in epithelial (H441, HCC827) and mesenchymal (H1299, HCC827_ZEB1) lung cancer cells." (PMID 36757799, 2023). "Given that PI4K2A localizes in endosomes and facilitates endosomal trafficking, we assessed PI4K2A as a mediator of ZEB1-dependent endosomal recycling, which has been shown to establish a polarity axis in lung cancer cells." (PMID 36757799, 2023). "Here, we show that PI4K2A stabilizes AXL and coordinates exocytic and endocytic trafficking of SPP1 and its receptors, respectively, to activate a protumorigenic autocrine loop in mesenchymal lung cancer cells." (PMID 36757799, 2023). "Indeed, miR-182 and miR-183 mimics decreased PI4K2A levels in H1299 and CALU-1 mesenchymal lung cancer cells and in HCC827_ZEB1, an epithelial LUAD cell line that has acquired mesenchymal properties owing to ectopic ZEB1 expression." (PMID 36757799, 2023). "Here, we show that miR-34a regulates PI4KB activity through this mechanism and that ZEB1 silences miR-34a and miR-182/-183 to coordinately inactivate PI4KB and increase PI4K2A levels, thereby executing a PI4KB-to-PI4K2A dependency switch that drives lung cancer progression." (PMID 36757799, 2023).
Orofacial dyskinesia (2 papers, 2022 to 2025). "The patients described here with pathogenic variants in PI4K2A show spastic paraplegia, orofacial dyskinesia, and intermittent dystonic postures of the upper limbs with clenched fist." (PMID 35880319, 2022).
colon adenocarcinoma (1 paper, 2023). "In this article, we aim to investigate the prognostic values of PI4K2A and provide new insights in colon adenocarcinoma (COAD)." (PMID 35634680, 2023).
colorectal cancer (1 paper, 2023). A primary or metastatic malignant neoplasm that affects the colon or rectum. "PI4K2A expression is aberrantly raised in colorectal cancer tissues in immunohistochemical microarrays in the HPA database." (PMID 35634680, 2023).
cutis laxa (1 paper, 2022). Cutis laxa (CL) is an inherited or acquired connective tissue disorder characterized by wrinkled, redundant and sagging inelastic skin associated with skeletal and developmental anomalies and, in some cases, with severe systemic involvement. "Importantly, neither of our patients with PI4K2A deficiency showed any signs of cutis laxa or joint hypermobility." (PMID 35880319, 2022).
glioblastoma multiforme (1 paper, 2016). "Given that PI4KIIα has roles in regulating both EGFR and AKT signalling, an initial aim of this study was to ascertain if the PI4K2A gene is mutated in glioblastoma." (PMID 25502460, 2016). "Astrocytomas and subsequently glioblastoma multiforme usually develop from astrocytes, and this prompted us to investigate whether PI4K2A mutations are associated with this disease." (PMID 25502460, 2016). "Structural rearrangements of chromosome 10 are frequently observed in glioblastoma multiforme and over 80 % of tumour samples archived in the catalogue of somatic mutations in cancer database had gene copy number loss for PI4K2A which encodes phosphatidylinositol 4-kinase type IIalpha." (PMID 25502460, 2016).
lung adenocarcinoma (1 paper, 2023). A carcinoma that arises from the lung and is characterized by the presence of malignant glandular epithelial cells. "To investigate the mechanistic basis for PI4K2A’s positive correlation with EMT, we used a panel of human lung adenocarcinoma (LUAD) and lung squamous carcinoma (LUSC) cell lines that have been classified as epithelial or mesenchymal and in which high ZEB1 levels maintain a partial EMT." (PMID 36757799, 2023).
microcephaly (1 paper, 2022). A congenital or acquired developmental disorder in which the circumference of the head is smaller than normal for the person's age and sex. "Patients with Vici syndrome also show microcephaly, corpus callosum abnormalities, and various movement disorders such as spastic paraplegia, similarly to our patients with PI4K2A deficiency." (PMID 35880319, 2022).
Salmonella Infections (1 paper, 2025). Infections with bacteria of the genus SALMONELLA. "Further, CrARFIP2KO cells showed a reduced number of LGALS3 spots during Salmonella infection, together with an increased association of ATG9A and PI4K2A with the bacteria." (PMID 40460835, 2025).
cancer (5 papers, 2016 to 2025). A tumor composed of atypical neoplastic, often pleomorphic cells that invade other tissues. "PI4K2A maintains cancer cell survival and promotes tumorigenesis by enhancing EGFR protein stability and by facilitating trafficking of misfolded proteins to the lysosome." (PMID 36757799, 2023). "Further studies are needed to determine the precise mechanism by which PKR interacts with lysosomes and confirm that Pac 1 targets the PI4K2A/PKR network in misfolded proteins that accumulate in cancer cells." (PMID 31554935, 2020). "Pac 1 binds to PI4K2A and disrupts the PKR/PI4K2A-associated lysosome complex, contributing to destabilization of cancer cell lysosomes and triggering cell death." (PMID 31554935, 2020). "Taken together, these results suggested that treatment with Pac 1 inhibits cancer cell growth via impairment of lysosome function triggered by disruption of the PKR/PI4K2A lysosome network." (PMID 31554935, 2020). "On the basis of these findings, we conclude that using Pac 1 to target PI4K2A/PKR lysosome networks is a promising approach to cancer therapy." (PMID 31554935, 2020). "A possible explanation is that other Golgi proteins, such as PAQR11 and PI4K2A, which are highly expressed in mesenchymal cancer cells, may compensate for the changes in Golgi morphology caused by ACBD3 loss." (PMID 40189704, 2025). "Moreover, many anti‐cancer drug sensitivities were negatively correlated with PI4K2A expression, providing some new ideas for the treatment of COAD." (PMID 35634680, 2023). "Signaling pathways including Chemokine signaling pathway, Hedgehog signaling pathway, MAPK signaling pathway, Pathways in cancer, and Toll‐like receptor signaling pathway may be the major regulatory pathways of PI4K2A." (PMID 35634680, 2023). "Next, we investigated whether Pac 1 disrupts the PI4K2A-associated PKR network and contributes directly to destabilization of cancer cell lysosomes." (PMID 31554935, 2020). "The Cancer Genome Atlas (TCGA) database, Human Protein Atlas online database, and UALCAN database were used to analyze the expression of PI4K2A in COAD and the survival of patients." (PMID 35634680, 2023). "Our findings demonstrated that treatment with Pac 1 binds to PI4K2A and disrupts PI4K2A/PKR network, contributing directly to destabilization of cancer cell lysosomes and triggering cell death." (PMID 31554935, 2020). "Our findings demonstrated that Pac 1 disrupts the PI4K2A/PKR network, contributing directly to destabilization of cancer cell lysosomes and triggering cell death." (PMID 31554935, 2020). "Treatment with Pac 1 disrupts the PI4K2A/PKR network, impairing lysosome function and inhibiting growth of various types of cancer cells in vitro and in vivo." (PMID 31554935, 2020). "To investigate as to how PI4K2A is engaged in the development of COAD, we conducted GSEA to find that PI4K2A may be involved in chemokine signaling pathway, hedgehog signaling pathway, MAPK signaling pathway, pathway in cancer, and Toll‐like receptor signaling pathway." (PMID 35634680, 2023).
tumor (5 papers, 2016 to 2023). "High levels of PI4KB, PI4KA, and PI4K2A are associated with a poor prognosis in multiple tumor types and drive malignant progression through distinct mechanisms." (PMID 36757799, 2023). "We investigated the relationship of PI4K2A with immune infiltration and tumor microenvironment in COAD using TIMER and ESTIMATE web tools." (PMID 35634680, 2023). "In recently, many researches have reported that PI4K2A is closely related to tumor development, but very few have focused on the connection between PI4K2A and the prognosis of COAD prediction." (PMID 35634680, 2023). "PI4K2A has been found to have a tumor‐promoting role in various solid tumors and be involved in various biological procedures." (PMID 35634680, 2023). "Additionally, other research has discovered that inhibition of PI4K2A along with EGFR inhibition better inhibits EGFR‐dependent tumor growth." (PMID 35634680, 2023). "In TCGA cohorts, PI4K2A mRNA levels are correlated with shorter survival durations in multiple tumor types, including LUSC, but not LUAD." (PMID 36757799, 2023). "Among all the PI4P producing enzymes high tumor PI4KA and PI4K2B expression is associated with poor overall survival in mHSPC patients, whereas the expression of other two PI4P producing enzymes PI4KB and PI4K2A do not have statistical significance." (PMID 37996444, 2023). "And whether PI4K2A acts endogenously or exogenously depending on the tumor, or both, we do not know yet." (PMID 35634680, 2023). "Furthermore, knockdown of PI4K2A did not affect 4T1 cell viability in vitro or 4T1 tumor growth in an orthotopic mouse model, but impaired the antitumor effect of diABZI on 4T1 tumors." (PMID 36280710, 2022).
movement disorder (3 papers, 2021 to 2025). Neurological conditions resulting in abnormal voluntary or involuntary movement, which may impact the speed, fluency, quality and ease of movement. "Interestingly, Ron Wevers and Eva Morava recently discovered a pathogenic variant in PI4K2A, encoding phosphatidylinositol 4‐kinase type 2‐alpha as the cause of a CL condition with strong neurological features, movement disorders and a marked myopathy." (PMID 33320377, 2021).
infection (2 papers, 2024 to 2025). The state of being infected such as from the introduction of a foreign agent such as serum, vaccine, antigenic substance or organism. "Overall, these data support a role for ATG9A and PI4K2A recruitment to the site of pathogen infection to mediate membrane repair and restrict pathogen infection and a regulation of these events by ARFIP2." (PMID 40460835, 2025).
neurodevelopmental disorder (2 papers, 2025). A behavioral and cognitive disorder with onset during the developmental period that involves impaired or aberrant development of intellectual, motor, or social functions. "Neurodevelopmental disorder with hyperkinetic movements, seizures, and structural brain abnormalities (NEDMSB) is caused by a homozygous mutation in the PI4K2A gene (MIM609763) on chromosome 10q24." (PMID 40182349, 2025).
PI4K2A also shares sentences with these, for which no sentence is quoted: brain malformations (1 paper); Dystonia (1); Epileptic encephalopathy (1); Failure to thrive (1); hepatocellular carcinoma (1); large cell carcinoma (1); myopathy (1); myotubular myopathy (1); neurodegenerative disease (1); Seizure (1); Spastic paraplegia (1); Vici syndrome (1).